INS (insulin)
Diseases named in the same sentence as INS in open-access papers (continued):
Sharing a sentence is not in itself a finding about the gene and the disease.
Insulin resistance (continued). "The fact that both obese and nonobese women living with PCOS were less insulin sensitive than their controls shows that although obesity may play a role in insulin resistance seen in this syndrome, there are other factors associated with PCOS implicated." (PMID 27672393, 2016). "In addition, unmeasured fetal or placental factors that influence insulin resistance may also have big impacts on antenatal insulin treatment." (PMID 27478440, 2016). "Our motivation for this approach is to investigate the effect of insulin resistance of an individual tissue on whole-body metabolism, in order to provide some insight into the order in which tissues may become insulin resistant in the development of type 2 diabetes." (PMID 27306890, 2016). "Furthermore, overexpression of CB1 or its specific activation in the liver leads to accumulation of long-chain ceramides in the liver that appear to mediate eCB-induced hepatic insulin resistance and development of hyperinsulinaemia as a result of reduced insulin clearance." (PMID 27105827, 2016). "Our aims here were to study the ethnic- and gender-specific prevalence of insulin resistance in relation to BMI and waist-circumference, and further to establish ethnic- and gender-specific BMI and waist-circumference cut-offs for corresponding insulin sensitivity." (PMID 27938404, 2016). "To determine whether the uterus exhibits local insulin resistance after chronic treatment with insulin and hCG, we performed a Western blot analysis to measure the expression of several proteins that are involved in the insulin-mediated PI3K/Akt signaling pathway." (PMID 27461373, 2016). "Second, the normal insulin sensitivity of the mother of the proband, despite obesity and genetic suppression of plasma adiponectin levels, suggests that primary adiponectin deficiency does not lead to highly penetrant insulin resistance." (PMID 27766312, 2016). "In addition, genetic predispositions to higher BMI and insulin resistance, but not to impaired insulin secretion, were associated with higher levels of BCAAs." (PMID 27898682, 2016). "Therefore, treatment with APE could enhance insulin action improving blood glucose levels and preventing insulin resistance." (PMID 27141227, 2016). "Additionally, in PCOS there is selective insulin resistance on the ovary, as reported for other tissues: insulin action on steroidogenesis is preserved, while insulin action on glucose metabolism is significantly decreased in granulosa-lutein cells from classical PCOS patients." (PMID 26875986, 2016). "Therefore, at 24 h following polytrauma skeletal muscle insulin resistance, as measured by insulin‐induced IR tyrosine phosphorylation, was evident by a decreased ability of the insulin receptors present to become phosphorylated/activated in response to insulin treatment." (PMID 26818585, 2016). "Notably, in vivo studies on insulin resistant obese patients showed increased ceramides levels in muscle biopsies and newly discovered evidence has identified C16:0-ceramide as the principal mediator of obesity-related insulin resistance." (PMID 27877101, 2016). "We found that individuals with an A1c of 6.5–7% exhibited an increased HOMA-β index compared with subjects who had an A1c < 6.5%, indicating that a slight increase in the A1c level may induce increases in insulin secretion, which occur to compensate for rising insulin resistance." (PMID 26640807, 2016). "It thus seems likely that insulin resistance and defective insulin delivery to the circulation may combine to produce especially severe glucose intolerance in PPARγ-/F:MORE+/Cre neonates and that this combination of defects does not persist in those animals that survive to adulthood." (PMID 27505464, 2016).
Insulin resistance (continued). "Indeed, mice lacking TLR-4 are protected against high-fat diet-induced obesity, inflammation, and insulin resistance because they are resistant to the suppression of insulin signaling during lipid infusion and exhibit reduced insulin-mediated changes in systemic glucose metabolism." (PMID 27881903, 2016). "In obesity, insulin often fails to adequately promote peripheral glucose uptake and suppress hepatic glucose production, resulting in hyperglycemia, which is associated with a state described as insulin resistance." (PMID 27226575, 2016). "Interestingly, GRK2+/− mice (expressing some 50% less protein than control littermates) show improved systemic insulin sensitivity in different insulin resistance models, and accordingly, inducible GRK2 downmodulation reverts key features associated to the diabetic phenotype in HFD-fed mice." (PMID 27832814, 2016). "Their findings, together with the non-significant result of our work, led us to postulate that circulating FGF21 may be associated with insulin resistance but not insulin itself." (PMID 26540514, 2015). "Analysis of key intermediates in the insulin signaling cascade has demonstrated sex-specific alterations that may be responsible for altered GLUT4 expression and reduced glucose uptake that is associated with states of insulin resistance." (PMID 25685986, 2015). "Therefore, keeping the normal phosphorylation of IRS-1 may be key to inhibit insulin resistance and improve insulin signaling." (PMID 25912041, 2015). "Thus, GD treatment can reduce insulin levels and ameliorate insulin resistance in diabetic mice." (PMID 26715102, 2015). "Though prospective cohort studies suggest that reduced ZAG expression in AT may be linked to the pathogenesis of insulin resistance, our data establish this adipokine as a negative modulator of insulin sensitivity." (PMID 26068931, 2015). "By acting on GIP receptors on adipocytes, GIP exhibits insulin mimetic properties such as elevation in glucose uptake, fatty acid synthesis, lipoprotein lipase synthesis, and reduction in glucagon-induced lipolysis; resulting in fat accumulation in adipocytes, obesity and insulin resistance." (PMID 26648813, 2015). "Also Scg5 (SGNE1) might impair glucose intolerance and insulin resistance, which was consistent with the insulin resistant phenotype of GK strain." (PMID 26529237, 2015). "Induction of vaspin mRNA expression might be a compensatory mechanism associated with obesity, severe insulin resistance, and the presence of T2DM, but it remains unclear whether there is a link between human serum vaspin levels and markers of insulin sensitivity and glucose or lipid metabolism." (PMID 25945347, 2015). "Therapy for T2D consists initially of dietary control and lifestyle modifications, followed by oral hypoglycemic agents, which may increase insulin secretion (for example, sulfonylureas) or reduce insulin resistance or hepatic glucose output (for example, metformin)." (PMID 25982967, 2015). "Consequently, it has been speculated that senescence and aging produce insulin resistance in ECs, but until now, the molecular mechanisms of the insulin resistance that occurs with senescence and aging have been unclear." (PMID 26338710, 2015). "Preeclampsia serum priming in adipose tissue leads to enhanced Th1 inflammation, oxidative stress, and insulin resistance, and simultaneously antiadipogenic induction may result in enhanced expression of Th2 predominance, antioxidative stress, and insulin sensitivity." (PMID 26089598, 2015). "Therefore, the relatively short term effects of exogenous insulin could be explained by a preconditioning of long exposure to endogenous hyperinsulinemia as a result of insulin resistance since the prediabetes stage." (PMID 26171401, 2015). "Moreover, the low insulin levels of ob/ob;Shp−/− mice may indicate that pancreatic β cells fail to appropriately compensate for insulin resistance by increasing insulin secretion." (PMID 25951943, 2015).
Insulin resistance (continued). "Individuals with NAFLD have an exaggerated β-cell insulin secretory response to an oral glucose load independent of BMI, age and sex; and a decline in β-cell index, which reflects pancreatic β-cell function in the setting of underlying insulin resistance." (PMID 26102213, 2015). "Moreover, although in vitro studies has shown a positive effect of anandamide in insulin secretion, whether diet-induced insulin resistance potentiates the insulinotropic effect of anandamide on the β-cells remains unknown." (PMID 25855974, 2015). "Indeed, it is estimated that 46% of AD patient have impaired fasting glucose and data suggest that a majority of AD patients have central insulin resistance, suggesting that impaired insulin signaling might be a part of AD pathological process." (PMID 26136681, 2015). "Despite the fact that this cut-off may not be adequate for other ethnicities, our results show clearly that the patients with MS have the lowest eGDR scores and therefore, they present with more insulin resistance, despite the apparently similar requirements of insulin." (PMID 26273680, 2015). "Interestingly, the range of membrane SM variations (from 17 to 59%) in SM-enriched cells was similar to that observed in adipocyte membranes of insulin-resistant obese patients compared with those of insulin sensitive patients, reproducing the situation found in human insulin resistance." (PMID 26230734, 2015). "However, elevated insulin secretion is difficult to interpret since (unlike the disposition index) it does not take account of the underlying level of insulin resistance, and is thus unable to provide a precise indicator of beta cell function." (PMID 25431266, 2015). "While first phase insulin release is delayed in both strains, there is a prolonged second phase insulin response in diabetic KO animals vs. WT animals, suggesting that KO mice may be experiencing greater peripheral insulin resistance." (PMID 26047815, 2015). "Vitamin D may play a role in glucose metabolism by enhancing insulin synthesis and release, and increasing insulin receptor expression or suppression of proinflammatory cytokines that possibly contribute to the development of insulin resistance." (PMID 26061015, 2015). "In addition to severe insulin resistance and diminished insulin response to incretin, intrinsic fragility of islets in ZFDM rats may contribute to the development of T2D in this strain." (PMID 25961052, 2015). "The physiological effect of SSB consumption on metabolic abnormalities may be explained by high dietary glycemic load leading to a postprandial rise in blood glucose and insulin concentrations, which over time may lead to hyperinsulinemia and insulin resistance." (PMID 26225136, 2015). "Lower insulin level after nicotine treatment in this study was well in line with the earlier finding that either acute or chronic nicotine exposures could negatively affect insulin action to develop insulin resistance both in smokers before the onset of type 2 diabetes (DM 2) and in DM 2 patients." (PMID 27486368, 2015). "Therefore insulin resistance with higher serum insulin levels and HOMA-IR may be modulated by higher serum adiponectin levels, especially in older females, as suggested by our multiple regression analyses." (PMID 25904939, 2015). "Similarly, it has been shown that mice with a beta cell pancreatic-specific ZnT8 knockout have glucose intolerance, while global ZnT8 null mice have abnormalities in diet-induced glucose tolerance and insulin secretion and have exacerbating diet-induced obesity resulting in insulin resistance." (PMID 25983752, 2015). "Additionally, while the significant decreases in plasma insulin concentration on the saury oil diet is likely due to a decrease in obese-related insulin resistance, glucose tolerance tests will be necessary in future studies to verify the effects of EPA- and LCMUFA-rich oils on insulin resistance." (PMID 26627187, 2015).
Insulin resistance (continued). "Depressed insulin sensitivity, or insulin resistance, is a metabolic state in which peripheral tissues, such as skeletal muscle, are no longer responsive to the anabolic effects of insulin, thereby reducing insulin-stimulated glucose uptake and perpetuating a state of hyperglycemia." (PMID 25685986, 2015). "In addition, the insulin sensitivity (as indicated by the insulin resistance index HOMA-IR) was also improved in the mice treated with either monotherapy or the combination therapy, and the greatest improvement occurred in the animals treated with the combination of the two agents." (PMID 25789330, 2015). "Moreover, BCAA supplementation reduced the risk of HCC in obese patients with chronic viral liver disease, demonstrating the clinical significance of lowering insulin levels and attenuating insulin resistance in the prevention of liver carcinogenesis in obese and diabetic patients." (PMID 25879666, 2015). "Therefore, MVs secreted by inflammation-activated macrophages may serve as potential inhibitors of insulin signaling and lead to insulin resistance in adipocytes." (PMID 26064180, 2015). "The findings that more women than men in BARI 2D were treated with insulin and that women were taking a higher number of units of insulin/kg of body weight daily when compared to men suggest the possibility of a greater degree of insulin resistance among the women." (PMID 25873955, 2015). "Obesity is the most important cause in the development of insulin resistance and several findings have shown that the critical determinant of insulin sensitivity and its related complications is not the degree of obesity “per se” but the distribution of fat partitioning." (PMID 25663838, 2015). "However, PKD has also been linked to increased fatty acid uptake under insulin resistant conditions, suggesting that impairment in PKD activity could contribute to cardiac lipotoxicity in insulin resistance." (PMID 25798941, 2015). "However, regardless of consumption of protein-only or carbohydrate-only, a small but significant increases in insulin levels and subsequent insulin resistance, as calculated using the homeostatic model of insulin resistance, was observed the morning following nighttime feeding." (PMID 25859885, 2015). "Thus, a subtle increase in insulin resistance due to visceral fat accumulation might well disturb the fine balance with the reduced insulin secretory capacity often seen in East Asians and easily trigger onset of type 2 diabetes." (PMID 25944304, 2015). "Hypersecretion of insulin may reflect beta-cell responses to different signals or a combination of an increased potentiating effect of glucose on beta-cells, long-lasting adaptation to severe insulin resistance and/or problems with the processing of insulin." (PMID 24791963, 2015). "However, some studies using mouse models found that metformin induced insulin resistance and hyperinsulinemia, which suggested that the anticancer effect of metformin may be mediated by reduced serum insulin levels." (PMID 25866823, 2015). "In addition, recent experimental studies have shown a direct effect of hyperuricemia on insulin resistance by increasing ROS release and inhibiting the insulin signaling pathway, thus supporting previous speculation." (PMID 26395162, 2015). "Thus, hyperinsulinemia with normal fasting glucose levels in HIAE girls may reflect insulin resistance, as suggested by the increased ratio of glucose to insulin." (PMID 26099471, 2015). "Moreover, we can postulate that autonomic imbalance or insulin resistance in SHR (or a combination of these) might contribute to the defective central action of insulin in control of HVGC." (PMID 25948821, 2015). "Therefore, additional studies, such as glucose tolerance, insulin tolerance, and/or euglycemic-hyperinsulinemic clamp tests, should be conducted to confirm whether metformin indeed ameliorates insulin resistance and glucose metabolism in the mouse model." (PMID 25879666, 2015).
Insulin resistance (continued). "Besides being obese, both mouse models also show slowly increasing glucose concentrations leading to hyperglycaemia, caused by obesity-associated insulin resistance and a lack of fully processed insulin and insulinotropic GLP-1." (PMID 26120850, 2015). "Lipotoxic effects of palmitate include impairements in insulin signalling, induction of insulin resistance, necrosis and apoptosis in different cell types are quite well known and other researchers indicated that palmitate exposure may induce hepatocytes apoptosis." (PMID 25635851, 2015). "We demonstrate that WAT NNMT expression is regulated in human insulin resistance and type 2 diabetes and that plasma MNA correlates with increased tissue NNMT expression and the degree of insulin resistance, making it a potential biomarker for loss of insulin sensitivity." (PMID 25596852, 2015). "Furthermore, the initial 75-g oral glucose tolerance test (75-g OGTT) performed at almost the same time showed impaired glucose tolerance with insulin resistance accompanied by delayed response of immunoreactive insulin (IRI) and a decreased insulinogenic index (ΔIRI/ΔPG) of 0.37 at 30 min." (PMID 26233654, 2015). "Thus, while it has been established that chronic hyperglycemia can lead to insulin resistance, research indicates that chronic hyperinsulinemia may also lead to reduced insulin sensitivity." (PMID 25710041, 2015). "The protection from HFD-induced insulin resistance in ApoA5 ASO-treated mice could be partially attributed to enhanced peripheral insulin sensitivity, as evidenced by increased peripheral glucose uptake and increased 2-deoxyglucose uptake in skeletal muscle and WAT." (PMID 25548259, 2015). "However, at present time, there is insufficient convincing evidence to conclude that LVM and prevalence of LV diastolic dysfunction are greater among subjects with low insulin sensitivity or insulin resistance, when adequate care is taken to adjust for DM, blood pressure, and body size." (PMID 26655187, 2015). "In obese children, relative body mass index, waist-to-hip ratio, serum lipid, glucose and insulin levels, as well as homeostasis model assessment of insulin resistance (HOMA-IR) scores were not different between Arg allele carriers (W64R and R64R) and noncarriers (W64W)." (PMID 25800470, 2015). "However, the most important mechanism to improve insulin resistance might be at the post-receptor level of insulin signaling." (PMID 26091235, 2015). "The release of non-esterified fatty acids may be the most important factor in modulating insulin sensitivity, and increased levels of non-esterified fatty acids are associated with the insulin resistance observed in obesity and type 2 diabetes." (PMID 25781947, 2015). "However a part of the controversy in addition to sex differences, might arise from higher plasma insulin concentrations which may develop as a compensation in insulin resistance." (PMID 26132582, 2015). "The present study uncovered a significant relationship between dairy consumption and reduced insulin sensitivity in middle-aged, nondiabetic women, suggesting that higher intakes of dairy products may be associated with greater insulin resistance." (PMID 25710041, 2015). "Decreased insulin sensitivity, or insulin resistance, is a critical precursor of the metabolic syndrome, as it is typically evident before other overt symptoms are apparent; and therefore it may represent an early, key step in the pathophysiological progression towards the metabolic syndrome." (PMID 25685986, 2015). "Although AMPK signaling has been highlighted as an important pathway associated with insulin resistance independent of the insulin-Akt signaling pathway, no studies have been conducted on the synchronous time course of impaired Akt and AMPK phosphorylation due to a HFD." (PMID 26266809, 2015).